ATG5 (autophagy related 5)
Diseases named in the same sentence as ATG5 in open-access papers (continued):
Sharing a sentence is not in itself a finding about the gene and the disease.
movement disorder (3 papers, 2016 to 2026). Neurological conditions resulting in abnormal voluntary or involuntary movement, which may impact the speed, fluency, quality and ease of movement. "Yeast models with the equivalent mutation showed a 30–50% reduction in induced autophagy, while Drosophila expressing the mutant human ATG5 exhibited severe movement disorders compared to those expressing wild-type ATG5." (PMID 41277110, 2026). "Flies in which Atg5 is substituted with the human mutant form (ATG5–E122D) were found to exhibit severe movement disorder, while flies expressing the wild-type human protein (ATG5-WT) were protected from such degeneration." (PMID 28737703, 2017). "Flies in which Atg5 is substituted with the mutant human ATG5 exhibit severe movement disorder, in contrast to flies expressing the wild-type human protein." (PMID 26812546, 2016).
retinopathy (3 papers, 2016 to 2024). "Endothelium-specific deletion of Atg5 reduces pathological neo-vascularization in a mouse model of retinopathy, and the retinal vascular hyper-sprouting phenotype induced by PKA deficiency is partially rescued by inhibition of autophagy or endothelium-specific Atg5 deletion." (PMID 33363161, 2020). "In this regard, it has been recently reported that the immunoproteasome degrades the autophagy-related proteins ATG5 and ATG12 in cardiomyocyte and retinopathy models, something that could be occurring in the context of hypothalamic neurons." (PMID 39095788, 2024).
gastrointestinal tumors (2 papers, 2017 to 2023). "In addition, a study analyzing gene ATG5 mutation and expression in gastrointestinal tumors showed that ATG5 protein was well expressed in normal colonic mucosal epithelial cells but was absent in 23% of CRC." (PMID 37168865, 2023). "We then examined the impact of transiently knocking down ATG5 or Beclin1 in other GI tumor cell types." (PMID 29245915, 2017).
kidney (2 papers, 2021 to 2024). "However, the role of macrophage-expressed Atg5 in acute kidney injury remains unclear." (PMID 38594728, 2024).
neurodevelopmental disorder (2 papers, 2014 to 2017). A behavioral and cognitive disorder with onset during the developmental period that involves impaired or aberrant development of intellectual, motor, or social functions. "Our results provide novel evidence for a role of ATG5 in CP and shed light on the molecular mechanisms underlying this neurodevelopmental disorder." (PMID 29326554, 2017). "Our results revealed that Atg5 has a crucial role in cortical neurogenesis during early embryonic brain development, which may contribute to the understanding of neurodevelopmental disorders caused by autophagy dysregulation." (PMID 25109817, 2014).
myopathy (1 paper, 2013). A disease of the muscle in which the muscle fibers do not function properly. "However, in an animal model of lysosomal storage Pompe disease due to GAA deficiency, the combined deletion of Atg5 worsens the myopathy, though permitting successful enzyme replacement therapy in autophagy deficient skeletal muscles." (PMID 23630012, 2013).
ATG5 also shares sentences with these, for which no sentence is quoted: Huntington disease (3 papers); lupus nephritis (3); malignant glioma (3); acute myocardial infarction (2); allergic rhinitis (2); Aortic dissection (2); brain injury (2); cardiac diseases (2); Crohn disease (2); dyslipidemia (2); fibrosarcoma (2); gastric adenocarcinoma (2); Glomerular sclerosis (2); hepatitis C (2); hypertrophy (2); hypothyroidism (2); Intellectual disability (2); Paget disease of bone (2); Parkinson's (2); prion disease (2); uremia (2); acute GVHD (1); acute pancreatitis (1); adrenocortical adenomas (1); Age-related cataract (1); amyotrophic lateral sclerosis (1); aristolochic acid nephropathy (1); Atrophy (1); autoimmune thyroid disease (1); B-cell lymphoma (1).
A further 77 diseases each share a sentence with ATG5 in 1 paper.